ALKBH5 (alkB homolog 5, RNA demethylase)
Diseases named in the same sentence as ALKBH5 in open-access papers (continued):
Sharing a sentence is not in itself a finding about the gene and the disease.
viral infection (20 papers, 2018 to 2025). "Viral infection of the host has been shown to cause disruption of host m6A-modifying demethylase ALKBH5." (PMID 40371106, 2025). "Our results showing reduced BCP-RNAs levels in HBV infected ALKBH5 silenced cells under hypoxic conditions supports a positive role for this demethylase in regulating susceptibility to viral infection." (PMID 38227578, 2024). "Taken together, it has been established that ALKBH5 is closely associated with bacterial/viral infection and immune system disorders; however, further investigations are required to fully explore the regulatory functions and underlying mechanisms of ALKHB5 in immune diseases." (PMID 40001461, 2025). "Despite different subcellular localization of ALKBH5 in response to different virus infection, depletion of m6A machinery including ALKBH5 generally leads to enhanced IFN antiviral response by regulation of the m6A RNA abundances (9, –, 13, 42)." (PMID 40793791, 2025). "Using the ALKBH5 antibody, similar binding profiles of ALKBH5 were also detected upon virus infection." (PMID 40793791, 2025). "During viral infection, the enzymatic activity of ALKBH5 is reduced in host cells, which leads to the downregulation of the α-ketoglutarate dehydrogenase (OGDH)-itaconate pathway associated with viral infection mediated by YTHDF2." (PMID 38957616, 2024). "As in viral infection, ALKBH5-mediated regulation of OGDH levels regulate TCA cycle activity and impact cellular metabolic fitness." (PMID 37742191, 2023). "Since DUSP1 inactivated p38 and JNK during bacterial and viral infections, and ALKBH5 knockdown reduced DUSP1 transcript stability by increasing the m6A level, we examined ALKBH5’s regulation of p38 and JNK activation." (PMID 36625590, 2023). "For example, host cells actively respond to viral infection by impairing the demethylation activity of ALKBH5 and thereby reprogramming the cellular metabolic state." (PMID 35835441, 2023). "The plant RNA m6A demethylases ALKBH10B and ALKBH9B (homologs of the human m6A demethylase ALKBH5) affect floral transition and viral infection." (PMID 37559087, 2023). "For example, in HIV and Enterovirus infection, viral infection can increase writer (METTL3/14 (methyltransferase 3/14)) and decrease eraser (FTO (fat mass and obesity-associated protein) or ALKBH5 (alkB homolog 5)) levels and thus promote viral replication." (PMID 37325513, 2023). "DDX3X plays an important role as a direct regulator of ALKBH5, mediating the modulation of demethylation of m6As during viral infections." (PMID 35897696, 2022). "A large portion of the upregulated and hypermethylated genes at 2 and 4 h were further upregulated following ALKBH5 knockdown, suggesting an important role of m6A hypermethylation for inducing these genes during bacterial and viral infections." (PMID 35288544, 2022). "Among DEDMs, those with hypermethylation and upregulation were the most common genes regulated by ALKBH5 during bacterial and viral infections." (PMID 35288544, 2022). "Knockdown of METTL3, METTL14, and YTHDF2 significantly increased viral infection and replication, while knockdown of ALKBH5 decreased viral infection and replication." (PMID 35465335, 2022). "And following researches in the field of viral infection reveal that ALKBH5 is involved in antiviral processes via m6A-guided regulation on cellular metabolism and innate immunity." (PMID 32772918, 2020). "By focusing on overlapped DEDMs between bacterial and viral infections, or bacterial infection and LPS treatment, we have identified sets of hypermethylated and hypomethylated genes that are either upregulated or downregulated following ALKBH5 knockdown." (PMID 35288544, 2022). "In summary, we have mapped m6A epitranscriptomes during bacterial and viral infections, and LPS stimulation, and identified m6A- and ALKBH5-regulated common and distinct innate immune response genes including a set of genes with positive correlation of expression with m6A level." (PMID 35288544, 2022).
viral infection (continued). "Upon viral infection, host cells impair ALKBH5 enzymatic activity to increase m6A methylation on α-ketoglutarate dehydrogenase (OGDH) mRNA resulting in reduced mRNA stability, protein expression, and decreased production of metabolite itaconate required for viral replication." (PMID 35288544, 2022). "ALKBH5 triggers inflammatory cascades by enhancing CD4+ T cell response during viral infections." (PMID 35897696, 2022). "In addition, ALKBH5 is a major epigenetic regulator of viral infection." (PMID 40001461, 2025). "Similarly, another DDX family member, DDX3, has been found to interact with ALKBH5 during the immune response, suggesting that this group of proteins may regulate viral infection by altering the abundance and stability of these molecules." (PMID 37325513, 2023). "ALKBH5 regulates p38 and JNK phosphorylation and their downstream innate immune response genes during bacterial and viral infections." (PMID 36625590, 2023). "Viral infection enhances the expression of METTL3/14 and DF1–3 at an early stage and decreases their expression at the late stage; however, the expression of ALKBH5 and FTO is consistently suppressed during infection." (PMID 37325513, 2023). "Together, transcriptome analysis identified hundreds of genes that are probably under the regulation of ALKBH5, including GAS6, which is a viral infection-related gene that we selected for further analysis." (PMID 35682869, 2022). "Indeed, the knockdown of DUSP1 or the m6A eraser ALKBH5 enhanced the expression of innate immune response genes, including IL-1β, CSF3, TGM2, and SRC, during bacterial or viral infections." (PMID 36625590, 2023).
depression (17 papers, 2018 to 2025). "Considering that METTL3, METTL14, and WTAP are core components of the methyltransferase complex, and FTO and ALKBH5 are major demethylases, it was reported that METTL3, FTO, and ALKBH5 were implicated in the pathology of depression." (PMID 37175269, 2023). "Du et al30 reported that SNP rs12936694 in the ALKBH5 gene plays a significant role in conferring to the risk of major depressive disorder in the Chinese Han population." (PMID 32091154, 2020). "Likewise, ALKBH5, another m6A eraser, was associated with depression in the Chinese Han cohort; however, these studies have yet to be replicated with larger sample sizes." (PMID 37047192, 2023). "The deletion of ALKBH5 resulted in a decrease in depression-related behavior under basal conditions and after social stress, and an increase in the basal anxiety levels." (PMID 40141416, 2025). "To investigate the mechanism by which astrocytic ALKBH5 regulates depression-related behavior, we collected mPFC tissues and performed m6A epitranscriptomic analysis by MeRIP-Seq." (PMID 38773146, 2024). "All findings point to the conclusion that astrocytic ALKBH5-m6A modulates depression-related behaviors." (PMID 38773146, 2024). "The astrocytic ALKBH5 cKO mice in our experiments exhibited antidepressant-like behaviors in FST and CSDS, and mPFC astrocytic ALKBH5 bidirectionally regulated depression-related behaviors." (PMID 38773146, 2024). "A recent analysis showed that there was an RNA m6A eraser ALKBH5 mutation in Chinese Han people with MDD, while the rs9939609 A mutation in the FTO gene was negatively correlated with depression." (PMID 36009052, 2022). "In a study on major depressive disorder, it was verified that circSTAG1 can bind to the demethylase ALKBH5 in the mouse hippocampus, decreasing ALKBH5 levels to alter the m6A level of FAAH mRNA and limit FAAH expression." (PMID 36212687, 2022). "In addition, ALKBH5 has been considered to be involved in the pathogenesis of mental disorders, such as depression and anxiety." (PMID 40001461, 2025). "Astrocytic ALKBH5 in the mPFC regulated depression-related behaviors bidirectionally." (PMID 38773146, 2024). "Our findings indicate that astrocytic epitranscriptomics contribute to depressive-like behaviors and that astrocytic ALKBH5 may be a therapeutic target for depression." (PMID 38773146, 2024). "To explore astrocytic ALKBH5 modulate depression-related behaviors via glutamatergic neuronal activity, we bidirectionally injected the AAV-CamkIIα-hM4D(Gi)-mCherry virus into the mPFC of Astrocyte cKO mice to specifically manipulate the activity of glutamatergic neurons." (PMID 38773146, 2024). "RNA methyltransferases (METTL3, METTL14, and WTAP) and demethylases (FTO and ALKBH5) are altered in the MDD patients and the mouse models of depression." (PMID 38773146, 2024). "Moreover, the astrocytic ALKBH5 in the mPFC regulated depression-related behaviors." (PMID 38773146, 2024). "Here, we reported that the ALKBH5, a well-characterized RNA demethylase, was increased in patients with MDD and mouse models of depression." (PMID 38773146, 2024). "In our present study on the relationship, we found that ALKBH5, an RNA demethylase of N6-methyladenosine (m6A), was increased both in the MDD patients and in the mouse models of depression." (PMID 38773146, 2024). "Here, we found that ALKBH5, an RNA demethylase of N6-methyladenosine (m6A), was increased in MDD patients’ blood and depression models." (PMID 38773146, 2024). "In one study, global m6A methylation is decreased in the whole blood of both human and mice after acute stress, and in another study, ALKBH5 and FTO as m6A demethylases and METTL3, METTL14, and WTAP as m6A methyltransferases are altered in the MDD patients and the depression models." (PMID 38773146, 2024).
depression (continued). "In the LPS-induced depression model, the demethylation function of m6A-modified PRMT2 mRNA is inhibited, resulting in increased expression of PRMT2 in BV2 cells and the hippocampus, while ALKBH5, SLC7A11, and GPX4 expressions decrease, facilitating ferroptosis." (PMID 40177374, 2025).
liver cancer (16 papers, 2020 to 2025). An epithelial or non-epithelial malignant neoplasm that arises from the liver. "In the context of liver cancer, ALKBH5 has been implicated in promoting tumor progression by enhancing immune evasion mechanisms within the tumor microenvironment." (PMID 39911396, 2025). "Elevated expression of ALKBH5 in liver cancer patients is strongly associated with the upregulation of immune-suppressive markers, such as PD-L1, which facilitate immune escape and contribute to tumor progression by impeding effective immune surveillance." (PMID 39911396, 2025). "Additionally, ALKBH5 has been implicated in regulating immune responses in the liver cancer-associated hepatitis microenvironment, thus offering new avenues for enhancing the effectiveness of liver cancer immunotherapy." (PMID 39911396, 2025). "ALKBH5 amplifies the characteristics of liver cancer stem cells by mediating the expression of SOX4 and activating the SHH signaling pathway, thereby conferring resistance to radiotherapy." (PMID 40823093, 2025). "ALKBH5 regulates liver cancer immunotherapy by modulating RNA demethylation, impacting tumor biology and immune responses." (PMID 39911396, 2025). "Given the complexity of its roles, future research should prioritize a deeper understanding of ALKBH5’s molecular mechanisms, particularly its downstream signaling pathways and functional variations across liver cancer subtypes." (PMID 39911396, 2025). "Transcriptomic analyses have demonstrated that ALKBH5 modulates both the intra- and extracellular liver cancer cell microenvironment, influencing macrophage polarization and hepatic cell transformation, thereby contributing to immune evasion in liver cancer." (PMID 39911396, 2025). "Studies have shown that when the expression level of ALKBH5 is reduced in liver cancer, it plays a role in inhibiting malignant tumors, while when the expression level is significantly increased, it indicates poor prognosis of liver cancer." (PMID 38166832, 2024). "For example, ALKBH5 has been reported to be involved in liver cancer development and immune microenvironment shaping, and IGF2BP3 promotes AML progression and stemness maintenance." (PMID 38822351, 2024). "ALKBH5 mRNA expression showed positive association with OS, PFS, and RFS rates of liver cancer patients." (PMID 35444654, 2022). "We used several authoritative liver cancer data sets and collected clinical samples to verify the high expression of ALKBH5 in liver cancer and its correlation with poor prognosis." (PMID 35982895, 2022). "At the human liver cancer sample level, we found that ALKBH5 was significantly related to the expression of HIF-1α, a key marker of hypoxia at the protein and mRNA levels, by investigating the Timer and CPATAC databases." (PMID 35982895, 2022). "Although our study mainly emphasizes the role of ALKBH5 in the immune microenvironment of liver cancer, further research is needed for some contradictions in previous studies." (PMID 35982895, 2022). "Some researchers have proposed that, as in liver cancer, new risk signatures constructed from 5 m6A-related genes (METTL3, METTL14, KIAA1429, ALKBH5 and YTHDF1) can be used as independent prognostic factors for PAAD." (PMID 34246319, 2021). "In liver cancer, high expression of writer, reader, and eraser proteins was associated with poor survival except METTL3, YTHDF3 and ALKBH5." (PMID 32863943, 2020). "In the realm of liver cancer immunotherapy, ALKBH5 plays a crucial modulatory role." (PMID 39911396, 2025). "The m6A demethylase FTO and ALKBH5 play roles in promoting liver cancer progression." (PMID 35945641, 2022). "Although the inconsistency in the degree of change may be attributed to the heterogeneity of the database which similar with some previous studies 6, these classic databases all suggest that ALKBH5 is upregulated in liver cancer 27-29." (PMID 35982895, 2022). "Dysregulation of the ALKBH5/LYPD1 axis promotes the development of liver cancer." (PMID 34246319, 2021).
liver cancer (continued). "In addition, ALKBH5 can promote PD-L1 expression in TAMs in liver cancer." (PMID 38872221, 2024). "Therefore, we emphasized on the role of ALKBH5 in liver cancer." (PMID 35982895, 2022). "However, it is necessary to further explore whether ALKBH5 has other mechanisms in liver cancer or its subtypes in the future." (PMID 35982895, 2022). "Together, these results indicate that both ALKBH5 and FTO regulate the expression of ATF4 in liver cancer cells treated with SOR." (PMID 39199320, 2024). "We detected multiple genomic HBV integrations in two distinct types of liver cancer, with recurrent events at TERT, ZMAT4, MET, ANKFN1, PLXNB2 in ICC, and TERT, ALKBH5 in CHC." (PMID 36123506, 2022). "The low-expression of demethylases (mainly FTO and ALKBH5) and concomitant m6A modifications in noncancerous peritumoral liver tissues are believed to enhance the malignant potential of liver cancer after resection." (PMID 34246319, 2021). "However, a study found that ALKBH5-mediated m6A demethylation resulted in the posttranscriptional inhibition of LYPD1 expression, which in turn may have inhibited the progression of liver cancer." (PMID 35945641, 2022).
esophageal squamous cell carcinoma (14 papers, 2020 to 2025). Esophageal squamous cell carcinoma (ESCC) is a type of esophageal carcinoma (EC) that can affect any part of the esophagus, but is usually located in the upper or middle third. "In esophageal squamous cell carcinoma, ALKBH5-mediated m6A removal is linked to regulating the lncRNA CASC8, which enhances cell growth and cisplatin resistance in ESCC." (PMID 38125749, 2023). "In esophageal squamous cell carcinoma, CSC can also cause the low methylation of DNMT1 and DNMT3a in the ALKBH5 CpG island, leading to the low expression of ALKBH5 and the downregulation of m6A levels." (PMID 40867537, 2025). "The eraser ALKBH5 is downregulated and acts as a tumor suppressor in esophageal squamous cell carcinoma by inhibiting m6A/DGCR8-dependent miR-194-2 biogenesis and releasing RAI1 expression, as well as through positive feedback between miR-193a-3p and ALKBH5." (PMID 39457524, 2024). "And it is reported that cigarette smoke condensate may induce the hypomethylation of ALKBH5 CpG island in esophageal squamous cell carcinoma." (PMID 32772918, 2020). "A previous study reported that a knockdown of ALKBH5 significantly increased the percentage of the tumor cells in the G0/G1 phase, along with the upregulated p21 protein expression, but suppressed cell proliferation and migration in the esophageal squamous cell carcinoma cell line." (PMID 36582218, 2023). "For instance, in ALKBH5 knockdown cells, the m6A level and stability of CDKN1A mRNA are upregulated, which enhances the expression of CDKN1A and suppresses the proliferation of esophageal squamous cell carcinoma (ESCC)." (PMID 40001461, 2025). "YTHDF1 restrains esophageal squamous cell carcinoma (ESCC) by interacting with long intergenic non-protein coding RNA 278 (LINC00278), but ALKBH5 harbors an opposite function." (PMID 32767982, 2020).
head and neck squamous cell carcinoma (13 papers, 2020 to 2025). A squamous cell carcinoma that arises from any of the following anatomic sites: lip and oral cavity, nasal cavity, paranasal sinuses, pharynx, larynx, and salivary glands. "Functionally, RBM33 is indispensable for the progression of head and neck squamous cell carcinoma (HNSCC): by recruiting ALKBH5 to demethylate and stabilize DDIT4 mRNA, RBM33 promotes autophagy and thereby drives tumorigenesis." (PMID 41562066, 2025). "Similarly, in head and neck squamous cell carcinoma (HNSCC), the level and function of NK cells are also inhibited by ALKBH5, mediating immunosuppressive TME and promoting tumor growth and progression." (PMID 39033180, 2024). "Specifically, in head and neck squamous cell carcinoma (HNSCC), the overexpression of ALKBH5 suppresses RIG‐I‐mediated IFNα secretion via the IκB kinase epsilon/TBK1/interferon regulatory factor 3 (IRF3) signaling pathway, which is closely related to tumor cell programmed cell death." (PMID 39802639, 2025). "In head and neck squamous cell carcinoma (HNSCC), knocking down ALKBH5 inhibits tumor progression." (PMID 37485079, 2023). "In head and neck squamous cell carcinoma, human RNA helicase DDX3 could modulate cisplatin resistance via ALKBH5-mediated m6A demethylation of FOXM1 and NANOG." (PMID 35279083, 2022). "In head and neck squamous cell carcinoma (HNSCC) cells, RNA-binding motif protein 33 (RBM33) recruits ALKBH5 to m6A-marked substrates and activates its demethylase activity by removing SUMOylation." (PMID 40186131, 2025).